FAM99B (family with sequence similarity 99 member B)
Synonyms: DKFZp781M09150
Gene: Long non-coding RNA gene on chromosome 11 (1,683,269 to 1,685,629, reverse strand). Ensembl gene ENSG00000205865.
Diseases named in the same sentence as FAM99B in open-access papers:
FAM99B is named in the same sentence as 4 diseases in open-access papers, as found by Europe PMC text mining. Sharing a sentence is not in itself a finding about the gene and the disease. The quoted sentences say what the papers report.
hepatocellular carcinoma (2 papers, 2020 to 2025). A malignant tumor that arises from hepatocytes. "Further, this study examined the effects of FAM99A and FAM99B on the metabolic pattern and rate of hepatocellular carcinoma cells using Seahorse assay." (PMID 40693878, 2025). "FAM99A and FAM99B suppress glycolysis, proliferation, invasion, and migration of hepatocellular carcinoma under hypoxic conditions, which may be related to the miR‐1291‐mediated ceRNA mechanism." (PMID 40693878, 2025).
liver cancer (1 paper, 2025). An epithelial or non-epithelial malignant neoplasm that arises from the liver. "We also appreciate recent findings discovered functions of FAM99B, as well as first attempts to apply liver‐targeted delivery based on GalNAc conjugates for liver cancer treatment using truncated FAM99B molecules." (PMID 40596757, 2025).
cancer (4 papers, 2017 to 2025). A tumor composed of atypical neoplastic, often pleomorphic cells that invade other tissues. "Another important co-expression pair comprised FAM99B and FTH1, pointing to a potential involvement in iron homeostasis and oxidative stress response, both of which are altered in cancer cells." (PMID 40248203, 2025). "In their results, 160 lncRNAs were found to be dysregulated in cancer, of which seven were found in our 658 lncRNA list (LOC645949, LINC00896, FAM99B, LINC00167, LINC01056, SND1-IT1, NCBP2-AS2)." (PMID 28415559, 2017).
tumor (3 papers, 2025). "In this study, we identified lncRNAs specifically expressed in the liver and found that FAM99B is frequently downregulated and functions as a tumor suppressor in HCC." (PMID 39952918, 2025). "Conversely, a higher expression of FAM99B was correlated with better patient outcomes, illustrating the diverse roles that lncRNAs may play in tumor progression." (PMID 40248203, 2025). "It is well known that hypoxia‐mediated glucose metabolic reprogramming is an important factor in tumor progression; therefore, we examined the effect of hypoxia on FAM99A and FAM99B expression in HCC cells (HEPG2, SK‐1 and HCCLM3)." (PMID 40693878, 2025).